VHL (von Hippel-Lindau tumor suppressor)
Diseases named in the same sentence as VHL in open-access papers (continued):
Sharing a sentence is not in itself a finding about the gene and the disease.
renal carcinoma (continued). "VHL deficiency in renal carcinomas can occur via inactivating mutations or allelic loss." (PMID 29435132, 2018). "In line with this, ectopic Notch1 ICD expression, which results in high levels of Notch signaling activation, increased normoxic HIF2α protein in primary breast cancer cells, human medulloblastoma cell lines D324 and DAOY, as well as the VHL-deficient 786-O renal carcinoma cell line." (PMID 29993038, 2018). "Our results illustrate how VHL and PBRM1 co-operate to drive renal transformation and uncover replication stress as an underlying vulnerability of all VHL mutated renal cancers that could be therapeutically exploited." (PMID 29229903, 2017). "Finally, to demonstrate that ZBRK1/VHL/p300 complex is associated with VHL promoter in renal cancer cells, we performed a chromatin immunoprecipitation (ChIP) assay focusing on a 105 bp fragment around the ZBRK1 site (−2145/−2041)." (PMID 25749518, 2015). "In the particular context of renal cancer, hypoxic signaling is frequently constitutively active owing to the majority of renal cancers presenting with clear cell carcinoma (ccRCC) histology, which is usually associated with mutational or functional inactivation of the VHL gene." (PMID 26441986, 2015). "For example, RB1 mutated and hypermethylated retinoblastomas phenocopy each other, colorectal tumours with either mutated or hypermethylated MLH1 have microsatellite instability (MSI) and VHL hypermethylation occurs in renal cancers of the clear cell histological subtype as do VHL mutations." (PMID 23341493, 2013). "In this report downregulation of miR-21 was found in VHL deficient RCC4 renal cancer cell line." (PMID 22685542, 2012). "The aim of this study was to provide a comprehensive analysis of VHL inactivation in clear cell renal tumors (ccRCC) and to evaluate relationships between VHL inactivation subgroups with renal cancer risk factors and VHL germline single nucleotide polymorphisms (SNPs)." (PMID 22022277, 2011). "VHL Type 2B families are more similar to Type 1 families, in that they carry more functionally deleterious mutations (partial gene deletions, nonsense mutations, and ‘deep’ missense mutations) that cause a high risk of renal cancer and a high risk of HB." (PMID 20560986, 2011). "Therefore, it is currently unclear what role HIF-α plays in VHL-associated tumors, especially with regard to initiation of renal carcinomas." (PMID 17598890, 2007). "Recently, it was postulated that deficiency of the von Hippel Lindau (VHL) protein, which is observed in most renal carcinomas, could be one of the factors responsible for downregulation of the biogenesis of complexes of the oxidative phosphorylation (OXPHOS)." (PMID 16404428, 2006). "Presence of an intact VHL protein in the tumour tissue could have explained the observed upregulation of the enzyme activities in the renal carcinoma tissue with the A3243G mutation." (PMID 16404428, 2006). "Although VHL mutations occur much less frequently in renal cancers other than ccRCC, our data support their functional significance when present, a finding that suggests molecular profiling may identify additional RCCs that would respond favorably to treatments targeting HIF signaling." (PMID 38969834, 2024). "We assume that VHL or PTEN mutations may contribute to the development of human renal cancer." (PMID 37445575, 2023). "Here, we demonstrated that inhibiting CK2 with the clinically relevant inhibitor CX-4945 in VHL-deficient renal cancer cells triggered a strong activation of phospho-ATM, suggesting that the benefit resulting from the combination of CK2 and ATM inhibition may be synergistic." (PMID 33540838, 2021).
renal carcinoma (continued). "Finally, transcriptome profiling of VHL− 786-O MCTS treated with our drug combination not only confirms our results but also opens perspectives to explore additional mechanisms driving apoptosis in VHL-deficient renal carcinoma cells upon cooperative blockade of CK2 and ATM kinases." (PMID 33540838, 2021). "The MMP dysregulation in renal cancer might be linked to VHL." (PMID 31200666, 2019). "Finally, by analyzing mRNA expression in human renal carcinoma samples in The Cancer Genome Atlas (TCGA), we have identified a correlation between VHL deficiency in RCC and reduced expression of HR and MMR genes, supporting the significance of our findings in human RCC." (PMID 29435132, 2018). "Thus, before conducting the experiments in the present study, we hypothesized that the activation of hypoxia-induced factors causes VHL-deficient renal cancer cells to be resistant to 2DG-ABT." (PMID 27460078, 2016). "However, HIF2α shows a key role in promoting VHL-deficient renal cancers." (PMID 26743088, 2016). "Thus, loss of some other VHL-associated function is required for initiation of renal carcinomas." (PMID 17598890, 2007). "It would also be of value to explore the interaction of PIEZO1 with known renal cancer drivers, such as VHL, HIF-1α, or mTOR, and to assess its impact on angiogenesis, metabolic regulation, and immune cell infiltration." (PMID 40724850, 2025). "Essential genes involved in the regulation of metabolic reprogramming in renal cancer are VHL, PTEN, Akt, mTOR, TSC1/2 and Myc." (PMID 38884097, 2024). "Overall, this study sets the stage for further exploration of the VHL-m6A axis and its implications in renal cancer biology." (PMID 38618952, 2024). "To explore the role of HIF2α in renal cancer cells, we stably inhibited HIF2α in three VHL(−/−) ccRCC cell lines (786-O, A498 and OS-RC-2) with lentiviruses carrying shRNA for HIF2α and a control nonspecific shRNA (LacZ)." (PMID 38263248, 2024). "The primary genes that control the process of metabolic reprogramming in renal cancer are Myc, VHL, PTEN, Akt, mTOR, and TSC1/2 48-52." (PMID 38169635, 2024). "VHL gene mutations and hypoxic conditions can lead to the upregulation of HGF and its receptor c‐Met in renal cancer." (PMID 39092291, 2024). "Depletion of VHL resulted in decreased global m6A levels in VHL-proficient renal cancer cells, with this regulation being mediated by VHL’s E3 ligase domain." (PMID 38618953, 2024). "For example, the VHL–HIF axis plays a pivotal role in renal cancer pathogenesis, with VHL inactivation and constitutive HIF activation driving angiogenesis and metabolic reprogramming." (PMID 39092291, 2024). "To start, we determined optimal conditions for target gene induction using RCC4 renal cancer cells re-constituted with WT VHL (RCC4+VHL) to restore oxygen-dependent HIF-α regulation." (PMID 36725335, 2023). "The tumor suppressor von Hippel-Lindau (VHL) is critical for renal cancer development, however, its role in kidney stone disease has not been fully elucidated until now." (PMID 37833251, 2023). "PBRM1 is a confirmed tumor suppressor when deleted with VHL in mouse models of renal cancer; however, PBRM1 deletion in most cells leads to either no change or context-dependent effects on growth rates." (PMID 36808431, 2023). "In renal cancer, SETD2 mutations are frequently associated with VHL, PBRM1, and BAP1 mutations as a result of chromosome 3p21 deletion." (PMID 37528416, 2023). "The most important genetic mutation in renal cancer tumorigenesis is the mutation of the von Hippel Lindau gene (VHL), a tumor suppressor gene encoding the von Hippel Lindau protein (pVHL)." (PMID 38053655, 2023).
renal carcinoma (continued). "The expression of SETD2 and VHL is positively correlated in patients with renal fibrosis and renal cancer, indicating their clinical significance." (PMID 37933774, 2023). "Together with the re-expression of key proteins that belong to BCAA catabolism, the reduction of SLC7A5 mRNA upon VHL re-expression confirmed that VHL loss is involved, at least in part, in the reprogramming of the BCAA degradation in renal cancer cells." (PMID 36539415, 2022). "Using this approach, we identified BCAA catabolism as one of the metabolic pathways strongly reprogrammed in renal cancer cells, whose transcriptional rewiring is sensitive to VHL restoration." (PMID 36539415, 2022). "This analysis revealed a consistent positive correlation of VHL-S65P signature with EMT score in the two cohorts of renal cancer patients, and hypoxia score in a cohort of patients with kidney cancer." (PMID 35505422, 2022). "The results showed that VHL levels in renal cancer correlated positively PD-L1 levels (r = 0.347, p = 0.011)." (PMID 36267974, 2022). "We transfected the VHL gene into renal cancer cell line 786-0, using the RT-PCR method at the transcription level." (PMID 35035522, 2022). "By query from multiple clinical data sets, we observed that the expression levels of this VHL-S65P genetic signature were significantly higher in human renal carcinoma specimens than adjacent normal tissues." (PMID 35505422, 2022). "Intriguingly, VHL is a key affected gene, occurring in approximately 60% of ccRCC, yet rarely in other renal cancer subtypes, such as papillary or chromophobe." (PMID 35445830, 2022). "VHL gene expression can significantly inhibit the proliferation ability of renal cancer cell line 786-0 and promote its apoptosis." (PMID 35035522, 2022). "Taking VHL as a target, transfecting it into renal cancer cells with appropriate methods, increasing the expression of the VHL gene, and correcting the apoptosis defects of tumor cells are very important treatment strategies." (PMID 35035522, 2022). "EME was shown to promote VHL-independent down-regulation of HIF-2ɑ in several renal cancer cell lines." (PMID 36139404, 2022). "Previous studies have pointed out that several lncRNAs that play vital roles in renal cancer are regulated by the VHL/HIFs axis." (PMID 35414787, 2022). "Examples of genes with a tissue-specific pattern of alteration include von Hippel Lindau tumor suppressor (VHL) in renal cancer, adenomatous polyposis coli (APC) in colorectal cancer, and KRAS in pancreatic, lung and colorectal cancers." (PMID 34143767, 2021). "In renal carcinoma cells, densitometry analysis revealed that the protein expression of VHL in cancerous tissue was lower when compared to normal adjacent tissue of the patients." (PMID 33419057, 2021). "CYR61 has been reported to be transcriptionally regulated by HIF proteins and to mediate the proangiogenic activity of VHL-mutant renal carcinoma cells." (PMID 34931765, 2021). "For the validation of CAIX targeting, we employed renal carcinoma cell lines that overexpress CAIX, reflecting the CAIX induction upon VHL mutation as widely seen in renal carcinomas." (PMID 34834361, 2021). "Integrating biochemical assays with molecular renal cancer cell analyses we show here that VHL binds to the key subunits of mTORC1, limits RAPTOR protein abundance, and suppresses mTORC1 signaling." (PMID 34290272, 2021). "There was a study that showed 5q amplification led to overexpression of the SQSTM1 oncogene in ccRCC lines and tumors, and the gene product of which, p62, regulated known renal cancer suppressor genes such as VHL, TSC1and TSC2 14,15." (PMID 31892969, 2020). "In our studies, we used a panel of renal cancer cell lines with different von Hippel Lindau (VHL) statuses." (PMID 32443455, 2020).
renal carcinoma (continued). "Considering these, we chose A498 (VHL-negative cell line) and SW839 (VHL mutant cell line) to study the effects of OMT on renal cancer by modulating β-catenin." (PMID 32581789, 2020). "In renal carcinoma, the upregulation of HIF-1 and constitutive activation of HIF-1 pathway occur due to a loss of tumor suppressor gene/function, von Hippel-Lindau (VHL), either by mutation or hypermethylation." (PMID 31941522, 2020). "Biallelic VHL inactivation is also required for the development of sporadic renal cancer, but requires a longer time than in VHL disease since the two VHL alleles must be inactivated." (PMID 32751108, 2020). "The role of Warburg’s effect in RCC has been widely confirmed and blocking the VHL-HIF-Glycolysis axis has been considered as a potential therapeutic strategy for renal cancer." (PMID 33287763, 2020). "Renal cancer, one of the most common malignancies of the urinary system, is characterized by frequent VHL gene inactivation and activation of the HIF–VEGF pathway, leading to extensive vascularization around kidney cancer." (PMID 32814829, 2020). "Our previous study demonstrated VHLα other than both VHL-19 and VHL-24 was capable of degrading hnRNPA2B1 in renal cancer cells." (PMID 32826868, 2020). "The NMU status of unfavourable markers in renal cancer was examined in cancer cells in relation to VHL (von Hippel-Lindau) protein." (PMID 31492042, 2019). "VHL is located in the short arm of chromosome 3 (3p25) and plays a central role in the development of renal cancer as a tumor suppressor gene." (PMID 30999623, 2019). "In summary, here we identified the oncogenic property of SNHG12 via miR-199a-5p-HIF1α pathway, which contributed to our comprehensive understanding of the hypoxia response in VHL-proficient renal carcinoma." (PMID 31114448, 2019). "Reconstitution of wild-type VHL protein (pVHL) in pVHL-defective renal carcinoma cells not only suppresses HIF activation and tumor growth, but also enhances mitochondrial respiratory chain function via mechanisms that are not fully elucidated." (PMID 30338240, 2018). "In this work, we inactivated VHL gene in a renal carcinoma cell line Caki-1 with CRISPR/Cas9 editing to find out which consequences this common oncogenic event directly caused for gene expression and DNA methylation." (PMID 30006568, 2018). "In the present study RCC-VHL mutational status was correlated to patients NK cytotoxicity through ex vivo evaluation toward human renal cancer cell lines A498 VHL-MUT and CAKI-1-VHL-WT." (PMID 30514329, 2018). "NK cytotoxicity was measured against specific target cells K562, VHL-wild type (CAKI-1) and VHL-mutated (A498) human renal cancer cells through externalization of CD107a and IFN-γ production." (PMID 30514329, 2018). "Overproduction of HIF-1α in VHL-defective renal carcinoma cells suppresses tumor formation, while overproduction of HIF-2α promotes tumor growth." (PMID 29560117, 2018). "To further explore the impact of combinational treatment of renal cancer cells, we analyzed cell growth and survival of 786-O VHL- cells grown as 3D multicellular tumor spheroids (MCTS)." (PMID 30046388, 2018). "Last, IDF-11774 significantly suppressed the tumor growth of Caki-1 renal cancer cells containing wild-type VHL and of 786-O cells with truncated VHL." (PMID 28569777, 2017). "The absence of VHL was even more distinctive in skin cancers as compared to renal cancers where VHL levels were medium or high in 7 out of 12 patient samples." (PMID 28806730, 2017). "While HIF is mostly active in hypoxic conditions, VHL-defective renal carcinoma cells show constitutive activation of HIF even in oxygenated environments." (PMID 27107416, 2016).
renal carcinoma (continued). "VHL-silenced renal carcinoma cells take on an elongated, fibroblastoid morphology while VHL(+) cells grow as clusters of cuboidal and rhomboid cells." (PMID 26967059, 2016). "Studies of hereditary kidney cancer syndromes have identified a series of rare, highly penetrant mutations in key genes, many of which have provided new insights into drivers of renal cancer, including, VHL, MET, FCLN, TSC1, TSC2, FH and SDH3." (PMID 27384883, 2016). "For example, although the mechanism of action by which EGFR is activated in ELSTs from patients with VHL remains to be determined, loss of VHL increases levels of the EGFR ligand, TGF-α, and activates EGFR in renal cancer cells." (PMID 26027747, 2015). "As our specialist interest lies in renal cancer research we chose to apply our methodology for the modification of genes known to be deleted in human renal cancer (VHL and TSC1)." (PMID 26046460, 2015). "In this report, the role of HIF-α in apoptosis was investigated using two parent VHL-null renal carcinoma cell lines." (PMID 25729330, 2015). "For example, VHL is targeted by miR-106a, miR-92a and miR-21, which have been found upregulated in renal carcinoma tissues." (PMID 28326269, 2015). "786-O and RCC10 renal carcinoma cell lines with manipulated levels of VHL, HIF-1α, or HIF-2α were subjected to cellular stresses and analyzed by western blotting for the abundance of apoptotic markers." (PMID 25729330, 2015). "Taken together, these findings suggest that ZBRK1 suppresses renal cancer progression perhaps by regulating VHL expression." (PMID 25749518, 2015). "Our finding that postnatal levels of pgc1β in the mouse heart are reduced in VHL null hearts supports the finding that HIF negatively regulates pgc1β expression in renal carcinoma cells." (PMID 24984146, 2014). "A method for enrichment of plasma membrane proteins using cell surface biotinylation and avidin affinity chromatography was optimised using the VHL-defective renal cancer cell line UMRC2-." (PMID 23970118, 2013). "The von Hippel-Lindau tumor suppressor E3 ubiquitin protein ligase has also been shown to down-regulate NDRG1 expression in renal cancer cells by targeting hypoxia inducible factor 1 for degradation." (PMID 24269992, 2013). "We used renal carcinoma cell lines that recapitulate the differences between mutant VHL and wild-type VHL genotypes." (PMID 23940778, 2013). "The results show the existence of functional crosstalk between two major tumor suppressors in renal cancer, VHL and FLCN, converging on regulation of autophagy." (PMID 23922894, 2013). "Hifα-independent function of VHL has been reported in driving kidney carcinoma, including regulation of senescence." (PMID 22685542, 2012). "A gene expression microarray comparing RCC10 renal cancer cells expressing either VHL or an empty vector was used to identify novel VHL regulated genes." (PMID 21791076, 2011). "HIF-1 activation shifts the balance of metabolism from oxidative phosphorylation toward glycolysis and mediates the Warburg effect in VHL-null renal carcinoma cells." (PMID 21709315, 2011). "When VHL expression was restored in VHL-null 786-O renal carcinoma cells or A498 renal carcinoma cells, VHL degraded endogenous p160." (PMID 21386990, 2011). "Restoration of VHL protein function is sufficient to suppress tumour formation in vivo in VHL-defective renal carcinoma cells." (PMID 21673679, 2011). "As a strategy to identify further potential targets, we examined the effect of re-expressing VHL in RCC10 renal cancer cells." (PMID 21791076, 2011). "Taken together these findings provide strong evidence that VHL regulates NMU expression in renal cancer cells via HIF." (PMID 21791076, 2011). "Here we demonstrate an autocrine NMU pathway in renal cancer cells that likely contributes to promoting migration of VHL expressing cells." (PMID 21791076, 2011).